IL10 (interleukin 10)
Diseases named in the same sentence as IL10 in open-access papers (continued):
Sharing a sentence is not in itself a finding about the gene and the disease.
tumor (continued). "Second, mouse tumor specimens were assessed for IL-2, IL-10, and CD4 levels by immunohistochemistry." (PMID 37253929, 2023). "M2-type macrophages can produce anti-inflammatory factors, such as IL-10, which can promote tumor cells’ survival, proliferation, and spread." (PMID 36903383, 2023). "Conversely, in macrophages-HOS and macrophages-143B co-cultures, the IL-10/IL-6 ratio increased after mifamurtide administration both in macrophages and in tumor cells." (PMID 37835437, 2023). "Arginase 1, TGF-β, and interleukin-10 (IL-10) derived from TAMs play a significant role in tumor immunosuppression." (PMID 36908706, 2023). "The release of HMGB-1 from tumor cells stimulated by hypoxia fosters IL-10 production in macrophages, which also supports an alternative activation." (PMID 37345046, 2023). "Here, we demonstrated that in metastatic OS cells, mifamurtide treatment alone was ineffective against tumor growth and that the tumor resistance was partly due to IL-10-dependent signaling pathway involvement." (PMID 37835437, 2023). "IL-10 is a multifunctional regulator playing a vital role in the body’s immune response, tumor growth or control, and inflammatory response, especially playing a central role in the anti-inflammatory response." (PMID 38067501, 2023). "In this phase, TME presents a balance between tumor-promoting cytokines (IL-10, IL-23) and antitumor cytokines (IL-12, IFN-γ)." (PMID 37345046, 2023). "The findings showed that higher a frequency of IL-10 + Tregs and IL-35 + Tregs correlate with tumor growth and invasion." (PMID 37221555, 2023). "This is mediated by the involvement of tumor-derived exosomes (TDEs) with low let-7s that mediate the production of cytokines (IL-6, IL-10) and induce N2 transformation." (PMID 37153744, 2023). "It was observed that IL-10 application was efficacious in the effector phase of tumor rejection, whereas application during tumor vaccination failed to significantly enhance tumor rejection." (PMID 37629156, 2023). "PPARδ inactivation not only significantly reduced IL-10+ Bregs in naïve mice, but also prevented IL-10+ Breg induction by tumor and anti-CD40 engagement." (PMID 37291146, 2023). "The hyposecretion of IL-2 and IFN-γ in peripheral blood is often detected in patients with advanced tumors, and the secretion of IL-10 increases, indicating that Th0 to Th2 differentiation is dominant during tumor growth." (PMID 36694223, 2023). "IL-10 is a tumor-promoting cytokines and its down-regulation suggests that CD8+ T cells without MK2 are potent dirver of anti-tumorigenic action and promotes gastrointestinal tumors regression." (PMID 37415974, 2023). "We found that IL-10, which plays an important role in the tumor microenvironment, upregulates HHLA2 in these myeloid immune cells." (PMID 37891555, 2023). "M2 macrophages release immunosuppressive molecules, such as IL-10 and transforming growth factor β, to promote tumor growth, while M1 macrophages produce pro-inflammatory cytokines like IL-1β and tumor necrosis factor." (PMID 37533789, 2023). "M2 macrophages are capable of synthesizing and releasing anti-inflammatory factors (TGF-β, IL-10, etc.), immunosuppressive factors and various tumor-promoting cytokines, which can suppress inflammatory responses and promoting tumor cell growth and metastasis." (PMID 37521424, 2023). "Bone marrow-derived MSCs were utilized for the targeted tumor delivery of the IL-10 gene to evaluate the anticancer potential of IL-10." (PMID 36742134, 2023). "Some studies have suggested that IL-10, as an immunosuppressive factor, can promote tumor immune evasion by inhibiting anti-tumor immune responses in the tumor microenvironment." (PMID 37910571, 2023). "This long-lasting tumor immunity is likely mediated by an IL-10 signaling pathway specific for intratumoral CD8+ T cells, IL-10-induced STAT1 and STAT3 phosphorylation, and IFN-γ expression in intratumoral CD8+ T cells." (PMID 37629156, 2023).
tumor (continued). "IL-10 is the most studied Th2 cytokine in the infectious and carcinogenic process due to the microenvironment favorable to tumor development, acting together with TGF-β." (PMID 37631922, 2023). "IL-10 is considered as one of the major immune suppressive molecules to promote tumor cell proliferation and metastasis." (PMID 37366887, 2023). "Tumor cells affect or limit the function of dendritic cells (DCs) antigen presentation via releasing growth factors and cytokines, such as vascular endothelial growth factor (VEGF) and IL-10, which finally leads to tumor immune escape." (PMID 36969152, 2023). "Melanoma tumor cells release HMGB1 in response to hypoxia, which promotes M2-like tumor-associated macrophage accumulation and IL-10 production, leading to an increased tumor growth and metastasis." (PMID 36982351, 2023). "By contrast, pro-tumor/anti-inflammatory TAMs have a phenotype associated with expression of CD206, ARG1, PD-L1 and secretion of IL10." (PMID 37469718, 2023). "IL-10 prevents dendritic cell (DC)-mediated apoptosis of tumor-specific CD8+ T cells through IL-10R signaling on DCs." (PMID 37586318, 2023). "TAMs are also known to promote tumor angiogenesis, tissue remodeling, and inhibition of the immune response producing IL-10, TGF-β and Indoleamine 2,3-dioxygenase (IDO) instead of IL-12." (PMID 37370706, 2023). "The role of IL-10 in modulating the tumor immune response appears to be dependent on the TME and the number of IL-10 receptors expressed on immune cells." (PMID 36835413, 2023). "Elevated levels of IL-10 and NLR are associated with increased tumor growth with poor prognosis and drug resistance." (PMID 38003396, 2023). "Tumoral cells can express suppressor cytokines (IL-6, IL-10, TFGβ, TNFα), which promote tumor growth and metastasis, suppressor cells (LT reg), and immunosuppressive molecules." (PMID 36830015, 2023). "IL-10 treatment also led to the generation of a tumor-protective immune memory capable of killing transplanted tumors, even up to 8 months after initial tumor rejection." (PMID 37629156, 2023). "M2 type macrophages generally promote tumour progression indirectly by secretion of growth factors and anti-inflammatory cytokines such as IL-10." (PMID 37612278, 2023). "Although the role of B lymphocytes in tumor immunity is less explored than T cells, they can promote tumor immunity mainly through IL-10 secretion." (PMID 37631922, 2023). "When bound to PD-1, PD-L1 can promote IL-10 expression, enhancing immunosuppress and thus leading to the escape of the tumor." (PMID 36765522, 2023). "Widespread acceptance as an immunosuppressive cytokine, interleukin-10 (IL-10), can diminish the antitumor immune response, thereby promoting tumor escape in the TME." (PMID 36765522, 2023). "Nevertheless, the role of other cytokines should also be taken into consideration for inducing tumor cells’ resistance to NK cell cytotoxicity (i.e., IL-10)." (PMID 37347290, 2023). "The immunosuppressive effect of IL-10 on dendritic cells and macrophages results in attenuated antigen presentation, allowing tumor cells to evade immune surveillance and impair cell maturation and differentiation." (PMID 38075864, 2023). "MDSCs and Tregs are more abundant in subtype A than in subtype B. Tregs can suppress CD8+ T cell activation and also secrete IL-10 and TGF-β to inhibit tumor-specific T cell infiltration and function, thereby causing immunosuppression." (PMID 36016566, 2022). "Cd36−/− BMDMs expressed lower M2 markers (Arg1, Cd206, Il-10) but higher M1 markers (Il-12, Tnfα) compared with WT BMDMs upon incubation with tumor cells or TCM." (PMID 36184646, 2022). "Administration of pegylated IL-10 resulted in the rejection of implanted tumors, accompanied by an increase in the number and functions of tumor-infiltrating CTLs." (PMID 35493517, 2022).
tumor (continued). "These cytokines are expressed in an altered manner; IL-1β, TNF-α, IL6, IL10, IFN-γ, and CX3CL1 are overexpressed and are correlated with the onset of pain, as it was discovered that they are linked to tumor progression and aggressiveness." (PMID 35054779, 2022). "The presence of cytokines IL-4, IL-10, and IL-13 secreted by OC cells and MSCs in the tumor niche is another signal for M2 polarization." (PMID 35269636, 2022). "In the meantime, Th2 cells express IL-4, IL-5, IL-6, and IL-10 and support tumor cell growth through CD40–CD40 ligand (CD40L) interactions in HL and Helicobacter-induced MALT lymphomagenesis." (PMID 35326620, 2022). "IL-10 can also induce tumor progression by inhibiting many cytokines such as IL-1a, IL-1b, IL-6, IL-8, IL-12, and IL-18." (PMID 35186043, 2022). "Mast cells promote tumor progression through the release anti-inflammatory cytokines, such as IL-10." (PMID 36430483, 2022). "After screening 12 candidate pro-inflammatory-to-anti-inflammatory pairs, only the IL-6/IL-10 mRNA expression ratio in tumor tissues had a significant effect on overall survival (OS) of STAD patients (P = 0.014)." (PMID 36371539, 2022). "IL-10, released from damaged cells, interacts with tumor microenvironment to reduce the antigen presentation rates and NK cell counts, suppressing the Th1-mediated responses thereby alleviating the monocyte and macrophage functionalities." (PMID 36675979, 2022). "In glioblastoma, it was demonstrated that purified astrocytes from tumor specimens showed a reactive state which is marked by response to IL-10 and IFNγ resulting in an activation of the JAK/STAT pathway." (PMID 35884845, 2022). "The M2d macrophages are induced by TLR agonists through adenosine receptors and highly express IL-10, which can induce angiogenesis and promote tumor cell growth." (PMID 36713445, 2022). "In detail, co-cultures of PBMCs with whole platelets or tumour cell-induced platelet releasates enhanced the release of IL-10 indicating a shift towards an immunosuppressive environment." (PMID 35285006, 2022). "TNF-α, IL-6, and IL-10 were all significantly higher in the Chemotherapy group compared with Tumor group." (PMID 36428795, 2022). "Previous studies suggested that IL10 can activate not only immune cells and immune functions, but also limitation of tumor occurrence and progression under specific microenvironments." (PMID 35637248, 2022). "Contradictorily, enhanced fatty acid oxidation in macrophages caused by fatty acids in tumor microenvironment results in increased ROS production and decreased IL-10 secretion to eliminate tumor cells." (PMID 36614031, 2022). "CAR-T20 increased human IFN-γ, murine TNF and murine IL-6 levels and decreased human IL-10 levels in tumor-bearing mice." (PMID 36352168, 2022). "Mice in both antagomir and antagomir NC group treated with anti‐IL10 antibody showed protection against tumour growth." (PMID 35969010, 2022). "Fourth, the high expression levels of IFN-γ,IL-12, and Nos2 and low expression levels of TGF-β, IL-10, andArg-1 in the tumor tissue confirmed that a strong tumor-specific immuneresponse had been elicited." (PMID 35926215, 2022). "On the other hand, there is also exist the regular B cells (Bregs) subset which can produce immunosuppression cytokines, such as IL-10 and IL-13, passively affects anti-tumor immunity." (PMID 36389757, 2022). "As the immunostimulatory ability of IL-10 is known to allow the expansion of tumor-resident CD8+ cells, our results suggest that IL-10 is indeed implicated in the maturation and differentiation of T cells in tumors of mice exposed to the oncolytic viral agent." (PMID 35454928, 2022). "In the context of ICB and TH1 cell cytokines, a recent study showed that tumor-infiltrating DCs express an increased IL-12/IL-10 ratio and more co-stimulatory molecules." (PMID 35563820, 2022). "In the present study, we expanded the application field of IL-6/IL-10 mRNA expression ratio into tumor tissues." (PMID 36371539, 2022).
tumor (continued). "Fourteen days of ACD7507 treatment significantly decreased pro-tumor cytokines IL-6 and IL-10 in tumor samples." (PMID 36077755, 2022). "Tumor cell IL-10 staining was detected in 68 (45%) patients with high expression observed in 42 patients." (PMID 35255925, 2022). "A series of histological staining, including immunohistochemistry (IL-6, IL-10, TGF-β and Navi1.7) and TUNEL were conducted to reveal the underlying mechanism of anti-tumor effect of CB/Lid-n on a VX2-tumor bearing model." (PMID 36221084, 2022). "It has also been suggested that IL-6, IL-22, and IL-10 can influence tumor drug resistance by regulating apoptosis-related proteins like BCL-2 and IAPs." (PMID 36245983, 2022). "The levels of IL-4, IL-10, and tumor markers (CA199, TSGF, and CEA) in the observation group were significantly lower than those in the control group (P < 0.05)." (PMID 36193493, 2022). "IL-10 was reported to promote the poor overall survival of cHL via genetic regulation of the tumor microenvironment." (PMID 35875135, 2022). "IL-10 in the tumor microenvironment inhibits the production of IFNγ and TNFα; it also downregulates MHC class II in monocytes, establishing TIL anergy, and, in doing so, it enhances tumor growth." (PMID 35203636, 2022). "The number of tumor-infiltrating Tr1 cells (CD4+ FoxP3- IL-13- IL-10+) was associated with tumor-infiltrating pDCs, which enhanced Tr1-produced IL-10 via ICOS-L when exposed to tumor-derived factors." (PMID 35619702, 2022). "The expression of M2 markers, including ARG1, IL10 and CD163 was higher in MADCAM1P270Q-reprogrammed tumor-associated macrophages (TAMs) and MADCAM1D242N-reprogrammed-TAMs, but lower or same in MADCAM1WT-reprogrammed-TAMs compared with control." (PMID 35449126, 2022). "The removal of ICOS-Fc from IL MIX resulted in it having a lesser effect on tumor growth (mass, volume), cell proliferation (Ki67), and immune modulation, in terms of IL-1β, IL-6, and IL-10 expression." (PMID 36500861, 2022). "Once peripheral blood monocytes are recruited to the tumor, they rapidly differentiate into the M2 macrophages via induction of IL-4 and IL-10 derived from tumor cells, Th2-polarized CD4+ cells and regulatory T cells." (PMID 35210436, 2022). "FACS analyses revealed i) increased CD11b+Gr1 + IL10+ myeloid cells, ii) decreased anti-tumor, M1 TAMs, and iii) markedly reduced infiltration of dendritic cells into the tumor microenvironment in IP6K1 KO mice." (PMID 35308129, 2022). "On the contrary, B cells can facilitate the progression of cancer by producing IL-10, inducing tumor angiogenesis and immunosuppression." (PMID 36569871, 2022). "TAMs can also secrete IL-10, IL-8, IL-12, and IL-35, which can promote the stemness characteristics of tumor cells." (PMID 35740975, 2022). "With high expression of ICOSL, tumor‐associated pDCs can recruit and activate ICOS+ Tregs and promote IL‐10 secretion." (PMID 34964283, 2022). "Regarding the expression of IL-10 in tumor tissues, studies reveal that it is significantly higher in HNSCC patients." (PMID 35740551, 2022). "Next, we determined the transforming growth factor β1 (TGF-β1) and IL-10, which are frequently overexpressed in tumor microenvironment and immunosuppressive cytokines related to MDSCs, macrophages, and Tregs." (PMID 35873573, 2022). "Among the differentially affected proteins, phosphorylation of epidermal growth factor receptor (EGFR) was highly increased in tumor cells treated with IL-10." (PMID 36038549, 2022). "As discussed, immunosuppression in PDAC is not induced by a single cell type or component, but by a combination of cells such as Tregs, MDSCs or CAFs, secreting multiple tumor-promoting mediators such as IL-10 or MMP9." (PMID 35205732, 2022).
tumor (continued). "CD4+ T cells contain two diverse subsets of helper T cells, namely, Th1 cells, which produce TNF-α, IFN-γ, IL-2, and IL-12 to mediate antitumor effects, and Th2 cells, which generate IL-4 and IL-10 and foster tumor growth by suppressing the host immune system." (PMID 36212483, 2022). "Secreting inhibitory factors like IL-4, IL-10, and IL-13, M2 macrophages show pro-tumor activity by promoting local immunosuppression, angiogenesis, and metastasis." (PMID 36405712, 2022). "To verify that miR‐192‐5p/RB1 promotes the Treg cell differentiation by IL‐10 secretion, we co‐cultured PBMCs with tumour cells under different conditions." (PMID 35969010, 2022). "The potential biological function was that TAM inhibits T cell activation and proliferation through IL10 to suppress anti-tumor immunity and promote tumor neovascularization." (PMID 35637248, 2022). "For instance, CD1dhiCD5+ Bregs produce IL-10 and downregulate the production of NO, TNFα, and the expression of activation markers by monocytes and macrophages limiting their anti-tumour activity." (PMID 35350071, 2022). "Bregs also secretes immunomodulatory cytokines such as IL-35 and IL-10, which induce Tregs production, stimulate tumor proliferation and promote local angiogenesis." (PMID 35965504, 2022). "TGF-β enhances macrophages’ production of IL-10 and drives the shift in the Th1/T helper type 2 (Th2) balance towards the anti-inflammatory and tumor-promoting Th2 response." (PMID 35335881, 2022). "Inhibiting TY2 blocks the activation of STAT3 by IL-10 and other pathways via T2, suppressing tumor cell survival via a bypass mechanism." (PMID 35211406, 2022). "IL-10 is known to be an anti-inflammatory cytokine reported to have mostly anti-tumor properties, based on experimental and clinical data, but pro-tumor actions have sometimes been reported based on in vitro and animal studies." (PMID 35948877, 2022). "Here, CD24+CD38+ Bregs promote tumour progression through a mechanism involving CD40 and CD40L interactions with cancer cells that subsequently leads to the secretion of IL-10 and TGFβ that sustain tumour proliferation." (PMID 35350071, 2022). "Remarkably, intratumorally injection of caerin 1.1 and caerin 1.9 in conjunction with an HPV16 E7 peptide-based vaccine containing IL-10 inhibitor and PD-1 blockade in tumor-bearing mice significantly suppresses tumor growth and prolongs their survival time." (PMID 35445137, 2022). "Immunosuppressive factors secreted by tumor cells, Tumor-associated macrophages (TAMS) and regulatory T cell (Treg) in the tumor microenvironment, such as IL-10, IL35, and TGF-β, are key factors in T cell failure." (PMID 35205714, 2022). "In TME, some tumor cells or tumor-associated cells secrete immunosuppressive factors, including TGF-β, IDO, PGE2, IL-6, and IL-10, which prevent NK cells from performing normal cytotoxic killing function." (PMID 35681736, 2022). "Meanwhile, cytokines such as IL-6 and IL-10 can further stimulate the secretion of IL-34 by tumor cells and immune cells and promote the expression of IL-34." (PMID 35936748, 2022). "Our observation that the tumor debris content following M-HIFU is strongly fragmented, prompted us to investigate the effect of M-HIFU and T-HIFU treatment on the levels of the immunosuppressive factors TGF-β and IL-10 in the resulting tumor debris." (PMID 36569907, 2022). "Breg cells suppress the anti-tumorigenic immune response and lead to tumor progression by the tumor-promoting cytokine IL-10." (PMID 36611932, 2022). "When comparing shMETTL3 and shMETTL3 + cisplatin to the control tumor, IL-2 was increased while IL-10 was decreased." (PMID 36429032, 2022). "The expressions of IL-10 in the tumor tissues generated from IL-10low LCL and IL-10high LCL were detected by immunohistochemistry." (PMID 35784354, 2022).